ALB (albumin)
Diseases named in the same sentence as ALB in open-access papers (continued):
Sharing a sentence is not in itself a finding about the gene and the disease.
Ascites (534 papers, 2003 to 2026). Accumulation of fluid in the peritoneal cavity (between the layers of the peritoneum that lines the abdomen). "Elevated IL-6 was associated with male sex, hepatomegaly, ascites, cherry angiomata, low albumin, endocrinopathy, reduced Diffusing Capacity of the Lung for Carbon Monoxide (DLCO), mixed sclerotic/ lytic bone lesions, and higher light chain values." (PMID 40646134, 2025). "Administration of albumin with diuretics in patients with ascites is associated with improved survival; however, little is known about the long-term use of albumin, particularly when combined with midodrine." (PMID 39912014, 2025). "This patient, who had significant loss of liver function, low albumin, and a small amount of ascites, was carefully observed." (PMID 40052123, 2025). "Factors such as low albumin levels, severe hydronephrosis, a high number of malignancy-related events, and the presence of metastases and ascites have been associated with worse survival." (PMID 39590154, 2024). "Reduced albumin production and an associated hypoosmotic state most likely contribute to the pathophysiology of ascites also in mPC patients." (PMID 36989885, 2023). "Age and liver-related variables, such as bilirubin, INR, albumin, platelets, and ascites, 30 days before surgery were associated with 30-day, 90-day, and 180-day mortality." (PMID 37763038, 2023). "In the next days, the patient's general conditions worsened, and he developed drowsiness and abdominal ascites; and diagnostic tap revealed high Serum Ascites Albumin Gradient (SAAG) ascites." (PMID 37484745, 2023). "In accordance with previous studies, univariate analyses showed serum AST, serum albumin, serum TBil, serum cholinesterase, platelets, serum sodium, ascites and bacterial infection were significant risk factors of liver failure." (PMID 36406414, 2022). "A serum albumin ascites gradient < 1.1 g/dL suggests other causes of ascites such as peritoneal carcinomatosis, tuberculosis, and other clinical conditions." (PMID 36064324, 2022). "Elevated CRP/albumin ratio was also associated with complications like multi-organ failure OR: 2.31 [1.3–4.2], duodenal thickening OR: 2.25 [1.2–4.2], and ascites OR: 2.90 [1.5–5.6]." (PMID 36268355, 2022). "The CP classification was applied to assess the hepatic function according to the risk stratifications of ascites, encephalopathy, serum ALB, TBIL, and prothrombin time." (PMID 35903263, 2022). "In our cohort, baseline presence of ascites, lower serum albumin, and higher serum INR levels were associated with the absence of liver function improvement in the univariate logistic regression analysis." (PMID 34817045, 2021). "The results of this study suggested that ascites ALB was another independent risk factor for liver cirrhosis complicated with SBP, consistent with another study." (PMID 30788303, 2018). "Factors associated with postoperative IAI were: preoperative weight loss, albumin ≤35 g/L, liver cirrhosis, preoperative ascites, operative time >300 minutes, operative blood loss >1000 mL, operative blood transfusion (P < .05 for all)." (PMID 28445320, 2017). "The prognostic factors associated with entecavir treatment included age, albumin, bilirubin, prothrombin time, ascites, hepatic encephalopathy and MELD score." (PMID 26703566, 2015). "DWs are positively associated with loss of work capacity, psychological abnormality, ascites, and active hepatitis B virus, while splenectomy and high albumin were protective factors for quality of life." (PMID 21358814, 2011). "Ascites in AP are caused by increased capillary permeability, subsequent fluid extravasation, and diminished colloidal osmotic pressure in blood vessels due to albumin consumption and mechanical exudation." (PMID 41446633, 2025).
Ascites (continued). "The decreased oncotic pressure due to serum albumin loss can trigger or exacerbate interstitial fluid accumulation (ascites, pleural effusion, etc.), which affects circulatory function, catabolism and anabolism, substance and drug transport, and increases the chance of infection." (PMID 38500655, 2024). "Besides the severity of ascites, two treatment-related factors were independently associated with its resolution: the dose of the albumin infused, and the serum albumin concentration achieved at 1 month of treatment." (PMID 39640220, 2024). "A very low albumin may cause formation of third spaces (pleural effusion, ascites) which may retain MTX for prolonged periods." (PMID 39305296, 2024). "As two parameters in the Child-Pugh score, serum albumin is strongly associated with ascites." (PMID 37612634, 2023). "CART itself is expected to improve ascites-associated symptoms (e.g. abdominal distension, general fatigue, dyspnea and loss of appetite) as palliative therapy, as well as renal dysfunction, while avoiding the use of an albumin preparation." (PMID 35287609, 2022). "Our data showed that ALB and serum Na+ levels were significantly decreased in liver patients with atrial arrhythmia, which may be associated with the development of ascites." (PMID 34291096, 2021). "A possible reason for finding is that decreased liver function could cause hepatic coagulopathy, lower albumin levels, and abnormal liver metabolism, which led to more severe complications, including ascites, infection, bleeding, and anastomotic fistulas." (PMID 34107967, 2021). "Serum ALB level is influenced by fundamental chronic liver dysfunction and mainly reflects the liver’s protein synthetic capability associated with severity of ascites." (PMID 32375846, 2020). "Indeed, the presence of ascites is caused not only by the portal pressure itself, but also by a deterioration of liver function and a lower level of serum albumin and sodium, which are closely correlated with the presence of ascites." (PMID 26949386, 2016). "The following variables were found to be independent diagnostic predictors of pleural effusion and/or ascites: degree of hemoconcentration ≥15.1 %, lowest albumin concentration at the critical phase ≤3.49 g/dL, lowest platelet count ≤49,500/μL, and elevated ratio of AST ≥2.51." (PMID 27391122, 2016). "Excessive albumin loss through the urine may accelerate the progression of hypoproteinemia, leading to ascites." (PMID 25436613, 2014). "However, these scores rely on variables such as biochemical markers, coagulation profiles, and clinical complications, making them vulnerable to fluctuations caused by symptomatic treatments like albumin supplementation, bilirubin reduction, and ascites management." (PMID 39119295, 2024). "The significant decrease of VV and PSP observed in the high-volume ascites group may be due to the pressure created by the high volume of ascites in the peritoneal cavity causing a collapse of vessels that blocked albumin-Gd-DTPA delivery and limited its extravasation." (PMID 30619738, 2018). "Serum albumin of patients with hyponatremia during hospitalization was lower than patients without, and this might be associated with the higher proportion of patients having ascites in the hyponatremic group." (PMID 26271263, 2015). "Compared with heart failure-associated transudative ascites, malignant ascites demonstrated higher levels of TNF-α, IL-6, IL-10, IL-12p70, IL-18, IL-23, s4-1BB, and TGF-β1, while albumin levels were lower." (PMID 42193466, 2026). "Covariate balancing propensity scoring matched the cohorts on baseline serum creatinine (SCr), presence of encephalopathy and/or ascites, albumin use and duration, age, and sex." (PMID 41472624, 2026). "Secondly, there are correlations between parameters such as serum albumin and the severity of ascites." (PMID 40052123, 2025).
Ascites (continued). "For the CTP score, the most notable between-group differences were observed in ascites, hepatic encephalopathy, bilirubin, and albumin subcomponents." (PMID 40444235, 2025). "The Child-Pugh score was calculated to be 7 points, comprising bilirubin (1 point), albumin (2 points), prothrombin time (2 points), ascites (1 point), and hepatic encephalopathy (1 point)." (PMID 40342900, 2025). "In this case, the patient exhibited hypoxemia, pleural and peritoneal effusions, hypotension, a significant decrease in plasma albumin levels on postoperative day 1, oliguria, hemoconcentration, and elevated creatinine levels." (PMID 40365489, 2025). "On the contrary, the MACHT trial recruited 173 patients with ascites listed for liver transplantation and randomized them into 40 g albumin every 15 days with midodrine, or placebo, on top of standard diuretic treatment." (PMID 40143117, 2025). "Ascites management involves restricting water and sodium intake, administering diuretics, albumin infusion, repeated paracentesis, and TIPS if necessary." (PMID 40417670, 2025). "The results of this study reinforced the emerging consensus that albumin was beneficial for the management of recurrent ascites in cirrhotic patients." (PMID 40662011, 2025). "Outcomes evaluated were the changes in serum albumin level, stool alpha-1 antitrypsin, and clinical symptoms such as, diarrhea, edema, weight change, and ascites." (PMID 40227431, 2025). "The study sought to determine the albumin's therapeutic benefits for cirrhotic patients with ascites to suggest optimal treatment approaches." (PMID 40662011, 2025). "Midodrine, along with octreotide and albumin, has been shown to improve ascites control in a short-term pilot study including patients with refractory ascites." (PMID 39912014, 2025). "A study had been designed to investigate the effects of intravenous albumin treatment on recurrent ascites in liver cirrhosis patients." (PMID 40662011, 2025). "Diuretics, antibiotics, and albumin should be administered early and reasonably to control the progression of ascites and SBP." (PMID 39958824, 2025). "The landmark ANSWER trial randomized 431 patients with diuretic-responsive ascites to receive either standard medical treatment or in combination with 40 g of albumin twice a week for the first 2 weeks and then 40 g weekly for 18 months." (PMID 40143117, 2025). "In this study, 431 patients with grade 2 and 3 ascites were administered with 40 g of albumin twice a week initially, and then 40 g once a week after the initial period." (PMID 38551716, 2024). "Third, preoperative parameters such as serum albumin, serum sodium level, and ascites volume are easily affected by treatment factors." (PMID 39403285, 2024). "The high SATI group exhibited significantly higher BMI, VATI, TATI, Hb, and albumin levels, as well as reduced Child-Pugh scores, a lower proportion of male patients, and a decreased incidence of ascites in comparison with low SATI group." (PMID 38185678, 2024). "Significant differences in preoperative recipient findings, including the MELD score, DM, ascites, and laboratory parameters, such as hematocrit, platelet count, albumin, total bilirubin, INR, and DFR, were identified in patients with and without AKI." (PMID 39336986, 2024). "The Child-Pugh classification estimates the prognostic stage of cirrhotic patients using four measures: serum albumin, bilirubin, prothrombin time, and ascites." (PMID 38872111, 2024). "The Albumin-Bilirubin (ALBI) score is another liver function index based solely on albumin and bilirubin levels, eliminating the need for subjective assessment of ascites and encephalopathy." (PMID 39421189, 2024). "In our study, comorbidities, as graded by ACE-27 from moderate to severe, were highly predictive of adverse surgery outcomes, when controlling for risk factors including albumin, CA125, SCS, and ascites on multivariable analyses." (PMID 38494480, 2024).
Ascites (continued). "In cirrhotic patients, ascites will present with a high serum/ascitic albumin gradient and low levels of protein in ascitic fluid." (PMID 38592411, 2024). "The incidence rate of ascites after 3 months was 46.0% (80/560) for patients with albumin levels < 3.2 g/dL before treatment and PVTT." (PMID 38583112, 2024). "On univariate analysis, ACE-27 score, SCS, albumin, CA125 at diagnosis, and ascites were statistically associated with grade III + complications or unintended ICU admission." (PMID 38494480, 2024). "The results revealed statistically significant differences between the groups in terms of age, ascites, ALB, PT, AST, PLT, PVV, PVD and ARFI." (PMID 38627672, 2024). "The factors described as associated with poor outcomes are a high Model for End-stage Liver Disease (MELD) score above 15, presence of ascites and albumin level below 3 g/dl, which are constituent definition of decompensated cirrhosis." (PMID 38017324, 2024). "One crucial element in the management of liver cirrhosis, especially in the context of complications such as ascites and acute decompensation, is albumin infusion." (PMID 38551716, 2024). "Symptomatic patients, including those with shortness of breath due to ascites, should receive a large-volume paracentesis preoperatively with an infusion of 6–8 g of albumin for each liter removed." (PMID 38966126, 2024). "In our patient who presented with 8000 ml of ascites, we supplemented a total of 60 g of 20% albumin during surgery." (PMID 39664174, 2024). "With PPG as the dependent variable, EVD, ALB, ascites, ALT, blood ammonia, PT, WBC, PLT, and TBiL were included to formulate a multivariate logistic regression equation." (PMID 39606628, 2024). "Calculating serum-ascites albumin gradient (SAAG) is fundamental in classifying the etiology of ascites." (PMID 38899262, 2024). "Albumin administration after an LVP (at a dose of 8 g/kg of tapped ascites, especially in the case of drainage of at least 5 L of fluid) is recommended to prevent the development of the so-called post-paracentesis circulatory dysfunction (PPCD)." (PMID 38592162, 2024). "In case 2, a positive CBNAAT for Mycobacterium tuberculosis explained the low serum ascites albumin gradient (SAAG <1.1) ascites." (PMID 39759723, 2024). "For example, in the evaluation parameters of CTP score, ascites and HE are subjective variables, the degree of ascites and serum ALB level are easily affected by treatment and their score ranges are narrow and have limited resolving power." (PMID 38750605, 2024). "Our nomogram established that factors such as CPS, serum albumin, total bilirubin, presence of ascites, GTV, presence of extrahepatic disease, previous liver resection, and primary colorectal carcinoma were predictive of OS." (PMID 39451740, 2024). "Other prognostic factors included levels of aspartate aminotransferase (AST), albumin, and the presence of ascites, encompassed in hepatic functional reserve classifications such as Child–Pugh and MELD." (PMID 38396674, 2024). "The CTP score incorporates three common laboratory indicators (prothrombin time, serum albumin, and bilirubin) as well as clinical indicators (ascites, hepatic encephalopathy and nutritional status)." (PMID 36761898, 2023). "PT or index, albumin, presence or severity for ascites, and MELD were reported as independent predictive factors for early bleeding or rebleeding after EVL." (PMID 38001426, 2023). "This score is based only on serum bilirubin and albumin level and eliminates subjective parameters such as encephalopathy and ascites included in CP score." (PMID 37374303, 2023). "We retrospectively analysed and compared the etiology, varicose veins, bleeding location, co-infection, ascites, portal vein thrombosis or tumor thrombus, albumin, platelets, prothrombin activity, and Child Pugh grade." (PMID 38357146, 2023).
Ascites (continued). "Historically, the CP classification (serum bilirubin, albumin, prothrombin time, severity of ascites, and encephalopathy) has been the most common assessment of hepatic function." (PMID 37046625, 2023). "Large-volume paracentesis (LVP > 5 L) with albumin infusion (8 gm/L of ascites removed) is the recommended therapy to relieve the symptoms." (PMID 37396918, 2023). "Decompensation manifested as mild-to-moderate ascites in 20/20 patients (100%) and led to an increase in total bilirubin and a decrease in serum albumin." (PMID 38137646, 2023). "The etiology, degree of varicose veins, bleeding location, treatment method, co-infection, ascites, portal vein thrombosis or tumor thrombus, albumin, platelets, thrombin were compared between the two groups of patients." (PMID 38357146, 2023). "There were statistically significant differences in age and sex among all the groups (p < 0.05), and there were significant differences in the levels of TBIL and ALB, PT and presence of ascites among all the analyzed groups (p < 0.001)." (PMID 37271809, 2023). "This score is based on five laboratory and clinical parameters such as ascites, hepatic encephalopathy, total bilirubin, albumin and prothrombin time or international normalized ratio (INR)." (PMID 37374303, 2023). "In the ANSWER study,78performed in patients with persistent ascites, favorable results were observed with albumin therapy, with a 38% reduction in the hazard ratio for mortality." (PMID 38101419, 2023). "This score is based on five simple parameters: encephalopathy, ascites, serum total bilirubin level, serum albumin level, and prothrombin time." (PMID 37927928, 2023). "Long-term albumin administration in patients with ascites improves survival, decreases hospitalization, and reduces overt HE, ascites, SBP, and non-SBP infections." (PMID 37396918, 2023). "Most supportive evidence for the use of albumin in patients with ESLD is available for fluid replacement after large-volume paracentesis (>5 L ascites), for patients with hepatorenal syndrome (HRS), and for spontaneous bacterial peritonitis (SBP)." (PMID 37218881, 2023). "The Child-Pugh scoring system is composed of several parameters, including serum bilirubin, serum albumin, prothrombin time, presence of ascites, and encephalopathy, which are utilized to forecast mortality risk among patients with liver cirrhosis." (PMID 37264303, 2023). "For non-BA parameters, increasing levels of creatinine, INR, protime, AST, bilirubin, AST/ALT, and MELD significantly increased the odds of developing ascites, whereas decreasing levels of albumin and ALT significantly increased the odds of developing ascites." (PMID 35402050, 2022). "This indicates higher serum albumin in the cirrhotic ascites patients, who also had a significantly higher (p < 0.001) mean serum tyrosine concentration (124 ± 73 μM) than the malignant ascites patients (44 ± 17 μM)." (PMID 35745058, 2022). "Compared to ALBI, the Child–Pugh score includes more subjective indicators (hepatic encephalopathy, ascites, bilirubin, albumin, prothrombin time)." (PMID 35810271, 2022). "A faster increase in serum albumin is desirable in dogs with inflammatory PLE so that complications such as ascites and thromboembolism can be avoided." (PMID 35739930, 2022). "Male sex, history of ascites, albumin levels, Child‐Pugh score, MELD score, ALP/ULN, GGT/ULN, ALT/ULN, AST/ULN and total bilirubin, were significantly associated with a reduced probability of biochemical response to OCA therapy according to Poise criteria." (PMID 35932095, 2022). "In multivariable analysis stratified to ascites grade, age, MELD score, and albumin were associated with mortality." (PMID 35845294, 2022). "In contrast, for every 20% increase in the albumin, the odds of developing ascites decreased 0.23-fold (OR: 0.231; P value < 0.05)." (PMID 35402050, 2022).